IL1B (interleukin 1 beta)
Diseases named in the same sentence as IL1B in open-access papers (continued):
Sharing a sentence is not in itself a finding about the gene and the disease.
gastric adenocarcinoma (15 papers, 2013 to 2025). "The interleukin-1B gene (IL-1B), interleukin-1 receptor antagonist gene (IL-1RN), and PPARγ Pro12Ala polymorphism act in HP-associated gastric adenocarcinoma." (PMID 38357448, 2024). "Interleukin-1β (IL-1β) has been implicated in the progression of gastric adenocarcinoma (GA); however, the molecular mechanisms of action of IL-1β in GA are poorly characterized." (PMID 24479681, 2014). "In a previous study, targeted overexpression of IL-1β in gastric parietal cells induced gastric adenocarcinoma by recruiting immunosuppressive MDSCs into the tumor microenvironment." (PMID 37543673, 2023). "Together with cagA+, IL-1β overexpression, it also increases the prevalence of gastric adenocarcinomas." (PMID 30854333, 2019). "A persistent stomach infection with H. pylori induces secretion of proinflammatory cytokines, including IL-1β, IL-6, IL-8, and TNF-α, which are closely linked to MALT-lymphoma and gastric adenocarcinoma." (PMID 30646625, 2019). "A recent report further demonstrated involvement of miR-425 in inflammation-induced cancer, which together with miR-191 and other miRNAs, has been shown to be upregulated in IL-1β-treated human gastric adenocarcinoma cell line AGS." (PMID 26207374, 2015). "To decipher the cellular state and function of macrophages in the process of intestinal-type gastric adenocarcinoma carcinogenesis, we reclustered all of the macrophages into five clusters, including macrophage_IL1B, macrophage_CHI3L1, macrophage_CXCL3, macrophage_IFIT3 and macrophage_FOLR2." (PMID 39702278, 2024). "In addition, the CagA protein, transcribed by the CagA gene, which includes two critical motifs, EPIYA and CRPIA, accounts for the high expression of proinflammatory cytokines (IFN-γ, IL-1β, and IL-8), DNA damage, gastric epithelial cell apoptosis, and gastric adenocarcinoma." (PMID 40264171, 2025). "Thus, it is not surprising that IL-1β has a pivotal role in initiating the development of gastric adenocarcinomas since inhibition of acid production is a significant step in developing gastric cancer." (PMID 30854333, 2019).
gastric tumors (15 papers, 2010 to 2023). "The association of gastritis and gastric tumor development has been shown to be strongly associated with genetic polymorphisms in the IL-1β locus." (PMID 30042333, 2018). "Since inflammatory cytokines, i.e. Il-1β, Il-6 and Il-11 have been associated with development of gastric tumors, we analyzed the hyperplastic antra of Gast−/− mice for the proinflammatory cytokines." (PMID 23110168, 2012). "Moreover, it is demonstrated that in a IL-1β-deficient mice model, the infiltration of immune cells and gastric tumors are positively suppressed." (PMID 30382864, 2018). "Gastric G-MDSCs were first identified in one study in which gastric-specific overexpression of IL-1β induced the appearance of these G-MDSCs within gastric tumors that developed in this mouse model." (PMID 37744359, 2023). "Inhibition of the JAK/STAT3 pathway in gastric tumor tissues reduces the inflammatory response, inhibits the inflammatory cytokines IL-1L, IL-6, and IL-1β, and decreases tumor volume." (PMID 34686626, 2021). "The current dogma supports the view that IL-1β promotes enrichment of MDSCs in the stomach thus balancing the alarmin activity of IL-1α, and can lead to gastric tumour formation." (PMID 25528766, 2015). "Similarly, IL-1β-/- mice were characterized by a reduction of H. pylori induced gastric tumors." (PMID 30042333, 2018). "Gastric tumours from WP1066- treated mice had reduced polymorphonuclear inflammation, coincident with inhibition of numerous proinflammatory cytokines including IL-11, IL-6 and IL-1β, as well as the growth factors Reg1 and amphiregulin." (PMID 24804649, 2014).
HCMV infection (15 papers, 2013 to 2025). "As far as ILs are concerned, SNPs of IL1B (rs16944 and rs3954) have been shown to be associated with cCMV infection and maternal HCMV infection." (PMID 34578364, 2021). "Human cytomegalovirus (HCMV) infection also induces the production of proinflammatory cytokines in inflammatory cells, including IL-1β, IL-6, IL-12, TNF-α, interferon-α/β and IFN-γ." (PMID 39459871, 2024). "cGAS/STING pathway activation contributes to increased IL-1β secretion after HCMV infection through the upregulation of AIM2." (PMID 34372578, 2021). "HCMV-infected (GFP-positive) cells showed significantly reduced Myc, a finding consistent with decreased IL-1β secretion and pro-IL-1β levels following HCMV infection." (PMID 30755509, 2019). "On the other hand, an AIM2 inflammasome-dependent IL-1β response to murine cytomegalovirus infection was reported in mouse macrophages." (PMID 28369146, 2017). "In summary, our data indicate that the HCMV tegument protein pUL83 binds to cellular AIM2, which partially contributes to the attenuation of the AIM2 inflammasome proteins 24 h post HCMV infection and reduced activation of caspase-1 and IL-1β." (PMID 28219398, 2017). "HCMV infection induces pro-inflammatory cytokine responses in inflammatory cells, with production of interleukin (IL)-1β, IL-6, IL-12, tumour necrosis factor (TNF)-α, interferon (IFN)-α/β, IFN-γ and prostaglandin E2 (PGE2)." (PMID 23722135, 2013). "HCMV infection activates the AIM2/caspase-1/IL-1β pro-inflammatory pathway." (PMID 34372578, 2021). "Since IL-1β secretion is impaired during live HCMV infection, we therefore asked whether any inhibitory effects on HCMV replication are detected in the presence of a functional inflammasome relative to such effects in cells in which it is not operational." (PMID 30755509, 2019). "Additionally, IL-1β secretion from endothelial cells, smooth muscle cells, and primary monocytes in response to HCMV infection has also been reported, in agreement with our results." (PMID 30755509, 2019). "Furthermore, dsDNA-responsive innate signaling induced by HCMV infection that leads to activation of the type I interferon response is also shown, unexpectedly, to play a contributory role in IL-1β secretion." (PMID 30755509, 2019). "(iii) Several researchers reported that HCMV infection induces the secretion of inflammatory cytokines such as interleukin (IL)-1β in serum of renal transplant recipients who developed a primary HCMV infection and IL-18 produced by HCMV-infected gingival fibroblasts." (PMID 28219398, 2017). "IL-1β mRNA is strongly induced following HCMV infection of MyD88-transduced cells, so we investigated whether IL-1β could be responsible for the blockade of HCMV spread by adding IL-1β to our monolayer of MRC-5 cells on d3 post-infection and every 3 days thereafter." (PMID 40638072, 2025). "The most important protein targets based on its degree from the C-T-P-D network were TNF, MAPK1, MAPK3, IL6, IL1B, AKT1 and CASP3 and the most important pathways associated with these protein targets were “Pathways in cancer”, “IL-17 signaling pathway”, and “Human cytomegalovirus infection”." (PMID 36591238, 2022). "We found that TOs secreted relatively few cytokines in response to HCMV infection, including pentraxin-3 (PTX3), first described as an endothelial factor induced by IL-1β treatment, IL-8, and IL-11." (PMID 35975985, 2022). "TNF-α, IL-6, and IL-1β at 24–28 weeks of gestation were significantly higher in women with GDM and HCMV infection than inthe other groups (all P < 0.01)." (PMID 35186501, 2022). "In particular, HCMV infection led mainly to the over-expression of CCL2, CCL3, CCL11, CXCR4, IL-1β, IL13, MMP1, MMP3, MMP9 and MMP13, SERPINA1, TNFα, and BMP7, and the gradual and constant downregulation of IL13RA2 (up to almost 800-fold at 14 days p.i.)." (PMID 32899126, 2020).
HCMV infection (continued). "This is interesting because HCMV infection seemed to lead to lower pro-inflammatory (TNF, IL1β, eotaxin, GMCSF) and Th2 (IL-4) reactivity to general T cell stimulation and the mycobacterial antigen PPD as compared to the HCMV- infants." (PMID 32582177, 2020). "The lack of impact of HCMV infection on measles-specific innate pro-inflammatory cytokines IL-1β and TNF, the Th1 cytokine IFN-γ, the Th2 cytokine IL-4 and the anti-inflammatory cytokine IL-10 is encouraging." (PMID 32582177, 2020). "Here, we used clustered regularly interspaced short palindromic repeat (CRISPR)–CRISPR-associated protein 9 (Cas9) genome editing to demonstrate that the dsDNA receptor absent in melanoma 2 (AIM2) is required for secretion of IL-1β following HCMV infection." (PMID 30755509, 2019). "Equally important, we show for the first time that a non-canonical pathway has evolved in response to HCMV infection, leading to inflammasome-independent maturation of IL-1β via caspase-8 activation." (PMID 30332797, 2018). "Lastly, we demonstrate that HCMV infection of HFFs triggers a non-canonical IL-1β activation pathway where caspase-8 promotes IL-1β maturation independently of caspase-1." (PMID 30332797, 2018). "Overall, these results indicate that HCMV infection leads to a decrease in intracellular IL-1β in a manner that is both independent of a viral block to pro-IL-1β transcription and consistent with our other observations illustrating virus- and IE86-mediated reduction in IL-1β secretion." (PMID 30755509, 2019). "Moreover, they found no changes in caspase-1 cleavage during HCMV infection, which led them to hypothesize that the canonical inflammasome assembly pathway does not play any role during enhanced IL-1β production upon HCMV infection." (PMID 30332797, 2018).
liver cirrhosis (15 papers, 2016 to 2025). "Methylobacterium has previously been identified as an opportunistic pathogen associated with increased levels of TNF-α and IL-1β in liver cirrhosis—a disorder characterized by dysbiosis, impaired intestinal function, and microbial translocation." (PMID 40871439, 2025). "Moreover, in patients with liver cirrhosis carrying the IL-1β risk haplotype, the likelihood of HCC was two times higher than in carriers of the CT haplotype." (PMID 36678401, 2022). "Gene polymorphisms of IL-10, IL-18, TGF-β1 have been confirmed to be related to liver cirrhosis by our study, however, it is accepted that IL-1β, IL-28, especially TNF-α plays an important role in the occurrence and development of liver cirrhosis." (PMID 37101651, 2023). "The presence of FokI SNP has been associated with decreased levels of the pro-inflammatory cytokine IL-1β and has been reported as an independent prognostic factor for survival in patients with liver cirrhosis." (PMID 37511164, 2023). "In this study, we aimed to assess the association of the common SNPs rs1143623, rs1143627, and rs16944 in the IL-1β gene with the development of liver cirrhosis and HCC in a large multicenter cohort of Caucasian patients with chronic HBV infection." (PMID 36678401, 2022). "The patient showed clinical features associated with hyperkeratosis, liver cirrhosis and increased serum IL-18 but not of IL-1β." (PMID 38907167, 2024). "CXCL1, IL-1β, and TNF-α were obviously increased in the liver cirrhosis group compared with the control group." (PMID 37273916, 2023). "Moreover, we next measured the levels of the inflammatory cytokines, including IL-6, CXCL1, IL-1β, and TNF-α, in the intestine to examine the role of liver cirrhosis on inflammatory response following vitamin D treatment." (PMID 37273916, 2023). "Genotype distribution of the IL-1β SNPs rs1143623, rs1143627 and rs16944 were not significantly different between patients with and without ultrasound signs of liver cirrhosis in the overall cohort." (PMID 36678401, 2022). "We show that in rats with chronic moderate hyperammonemia, similar to that present in patients with liver cirrhosis, neuroinflammation in hippocampus alters membrane expression of AMPA receptors mainly through activation of IL-1 receptor by increased levels of IL-1β." (PMID 29422059, 2018). "However, the impact of the IL-1β polymorphisms was independent of the phases of chronic HBV infection, and the presence of liver cirrhosis enhanced the effect." (PMID 36678401, 2022). "Mechanistically, NLRP3 inflammasome-activated GSDMD and its pyroptosis were upregulated in liver cirrhosis, while SHED infusion could suppress the expression of GSDMD and Caspase-1, resulting in reduced hepatocyte pyroptosis and inflammatory cytokine IL-1β release." (PMID 35634294, 2022).
lymph node metastasis (15 papers, 2007 to 2026). "Gene polymorphism evidenced that IL-8 may contribute to DTC lymph node metastasis, and IL-1β may cause PTC lymph node metastasis." (PMID 32655554, 2020). "Regarding lymph node metastasis, IL-1β and IL-6 demonstrated increasing levels with an advancement in the N stage, IL-6 demonstrating the most important differences between N stages." (PMID 38137862, 2023). "IL1B rs1143643 was related to lymph node metastasis of papillary thyroid carcinoma in Korean patients." (PMID 33472637, 2021). "IL-1β, IL-6 and IL-10 immunostaining was significantly higher in tumour and lymph node metastasis than in MSR squamous epithelium (p<0.001)." (PMID 31870104, 2019). "This is also supported by the fact that IL-1β silencing reduces OSCC tumor size in vivo and that elevated IL-1β expression has been related with lymph node metastasis in OSCC." (PMID 38473882, 2024). "This is also supported by the fact that IL-1β silencing reduces OSCC tumor size in vivo and that elevated IL-1β expression has been related with lymph node metastasis of OSCC." (PMID 35048046, 2021). "Furthermore, case 10, which showed the strongest staining for IL-1β, was diagnosed as early stage without distant metastasis or lymph node metastasis." (PMID 31816951, 2019).
macrophage activation syndrome (15 papers, 2019 to 2025). A complication of rheumatic disease that is caused by excessive activation and uncontrolled proliferation of T lymphocytes and well-differentiated macrophages. "Even in the case of a Macrophage Activation Syndrome (MAS), where IL-18 has a causal effect, the patient received combined IL-1β and IL-18 blockade for 11 months." (PMID 36668761, 2022). "These symptoms are associated with excessive levels of IL-18 and IL-1β, and recurring fever flares, a phenotype that is reminiscent of macrophage activation syndrome (MAS)." (PMID 31520179, 2019). "NLRP3 regulates the secretion of proinflammatory cytokines interleukin 1 beta (IL-1β), a key cytokine in the development of inflammatory syndromes such as macrophage activation syndrome." (PMID 32423059, 2020). "Hyperinflammation and macrophage activation syndrome (MAS) result in the overproduction of proinflammatory cytokines, such as the IL-1β, IL-6, and TNFα, as well as coagulation abnormalities, which contribute to organ failure and other fatalities." (PMID 35495698, 2022). "Cytokine storm, defined as macrophage activation syndrome (MAS), is characterized by the release of multiple pro-inflammatory cytokines (IL-1β, IL-18, IL-6, IL-2, IL-7, TNF-α) and chemokines (CCL2, CCL3) from macrophages." (PMID 35008658, 2021). "Subjects with macrophage activation syndrome had higher serum C reactive protein (CRP), ferritin, and IL-1β levels and lower white blood cell count than those with lymphocyte depletion." (PMID 32423059, 2020). "For example, pyrin and NLRP3 are widely expressed in innate immune cells and activate pro-IL-1β, while NLRC4 is expressed in the gut and has pro-IL-18 as substrate, contributing to the development of severe enterocolitis and macrophage activation syndrome (MAS)." (PMID 34198614, 2021).
post-traumatic stress disorder (15 papers, 2016 to 2025). An anxiety disorder precipitated by an experience of intense fear or horror while exposed to a traumatic (especially life-threatening) event. "In addition, the post-traumatic stress disorder (PTSD) is associated with increased levels of IL-6, interleukin-1 beta (IL-1β), interferon gamma (INFγ) and tumor necrosis factor alpha (TNFα)." (PMID 32858844, 2020). "The mRNA expression level upregulated by ligature is a 1.5-fold change compared with the control, consistent with previous data showing that posttraumatic stress disorder increased IL-1β expression approximately 1.5-fold, which is connected with neurodegenerative disorder." (PMID 32992470, 2020). "Pro-inflammatory cytokines, known to increase in post-traumatic stress disorder (PTSD) and major depressive disorders, are known to regulate synaptic strength and synaptic plasticity in the nervous system, thus so studies involving IL-1β were conducted." (PMID 34205595, 2021). "In animal models of post-traumatic stress disorder (PTSD), S-ketamine has been shown to attenuate pro-inflammatory responses by reducing TNF-α and IL-1β levels in critical brain regions such as the striatum and periaqueductal gray." (PMID 41369360, 2025).
thyroid cancer (15 papers, 2017 to 2025). "It was reported that IL1B polymorphism is risk factor for thyroid carcinoma in a Chinese Han population." (PMID 37898675, 2023). "Rs1143643 in IL-1B increased the susceptibility to thyroid carcinoma under the allele (OR = 1.26, 95% CI 1.05–1.52, p = 0.013), genotype (OR = 1.61, 95% CI 1.10–2.34, p = 0.014), dominant (OR = 1.42, 95% CI 1.04–1.94, p = 0.027), and additive (OR = 1.27, 95% CI 1.05–1.53, p = 0.015) models." (PMID 33472637, 2021). "IL-1α and IL-1β, encoded by the IL1A and IL1B genes, promote inflammatory responses and tumor progression in thyroid carcinoma." (PMID 40823082, 2025). "IL1B polymorphisms were associated with an increased thyroid cancer risk after the fifth decade of life (>48 years old), whereas IL1A polymorphisms and thyroid cancer susceptibility were linked to age below this threshold." (PMID 37189693, 2023). "IL-1β exerts strong antitumor effects on thyroid carcinoma by inhibiting proliferation and invasiveness." (PMID 33472637, 2021). "Immunohistochemical expression of RORγt, IL-23 and IL-1β can be easily accessed in routine pathology laboratories helping to predict the prognosis of patients with thyroid cancer and better individualize their clinical management." (PMID 32139737, 2020). "Recently, wedescribed a similar NF-κB-dependent co-regulation of QPCT and CCL2 inepithelial cells of thyroid carcinomas upon TNF-α/IL-1β treatment." (PMID 28739588, 2017). "Twelve SNPs of IL1A and IL1B were examined, concluding that six of them (rs3783521, rs3783546, rs3783550, and rs1609682 for IL1A and rs3136558 and rs1143623 for IL1B) were linked to an increased susceptibility to thyroid cancer development." (PMID 37189693, 2023). "Furthermore, IL-1β did not have an anti-proliferative effect on ATC cell lines, which indicates that PTC cancer cells escaping from antitumor effect of IL-1β may be a step toward anaplasia change, resulting in more aggressiveness of thyroid cancer." (PMID 32655554, 2020). "While our study focused solely on patients with PTC within the thyroid cancer category, the PTC group exhibited significantly lower IL-1β levels than the control group." (PMID 40150133, 2025). "Chronic inflammation enhances thyroid cancer progression, with TNF‐α and IL‐1β known to promote tumor invasiveness and survival." (PMID 41477125, 2025). "A prior study involving 20 thyroid cancer patients and 50 healthy controls found that the thyroid cancer patient group had lower IL-1β levels than the control group, but the difference was not statistically significant." (PMID 40150133, 2025). "Previous clinical studies have suggested that IL-1β, IL-2, IL-27, and tumour necrosis factor (TNF)-α could serve as biomarkers for the diagnosis and monitoring of thyroid cancer progression." (PMID 40892159, 2025). "Compared with healthy controls, IL-1β was found to be underexpressed in the serum of patients with PTC, and it was considered to be a valuable factor in discriminating atrophic thyroiditis and thyroid cancer." (PMID 32655554, 2020). "Such a regulated expression of QC, but not isoQC, was already reported for thyroid carcinomas and for Human Umbilical Vein Endothelial Cells (HUVECs) after stimulation with TNF-α/IL-1β." (PMID 39272984, 2024).